INS (insulin)
Diseases named in the same sentence as INS in open-access papers (continued):
Sharing a sentence is not in itself a finding about the gene and the disease.
glaucoma (continued). "In summary, our study provides a compelling example of vision restoration by insulin administration offering the possibility of developing this strategy for the treatment of glaucoma and other optic neuropathies." (PMID 39110798, 2024). "Brain insulin resistance or central insulin signaling dysfunction is thought to contribute to transsynaptic neurodegeneration in glaucoma." (PMID 37620923, 2023). "Based on epidemiological and experimental studies, the insulin signaling pathway is a promising target for neuroprotection in neurodegenerative diseases, including AD, PD, and glaucoma." (PMID 33925119, 2021). "The results also show that patients treated with sulfonylureas, glitazone, and slow-acting insulin in combination with rapid-acting insulin have a significantly higher HR for developing glaucoma compared to patients treated with rapid-acting insulin analogues." (PMID 27872861, 2016). "The application of topical insulin proved safe and well-tolerated among patients with glaucoma." (PMID 41584099, 2026). "These preclinical data suggest human recombinant insulin may serve as a promising treatment for optic neuropathies such as glaucoma." (PMID 41584099, 2026). "Here we evaluate the safety and efficacy of topical insulin in human patients with glaucoma." (PMID 41584099, 2026). "On the contrary, MD significantly worsened in the insulin glaucoma group (p = 0.01) at T6." (PMID 41285704, 2025). "Although clinical trials in glaucoma are yet to be conducted, preclinical evidence suggests that exogenous insulin may help preserve RGCs." (PMID 39458902, 2024). "To investigate whether insulin can stimulate dendritic regrowth, we characterized the response of RGCs to ocular hypertension (OHT), a major risk factor to develop glaucoma." (PMID 39110798, 2024). "Collectively, improving IR or insulin signaling activation could be a promising target for glaucoma treatment." (PMID 38952394, 2024). "This suggests that IR plays a critical role in the pathogenesis of glaucoma, and improving insulin sensitivity could be a potential therapeutic target." (PMID 38952394, 2024). "Targeting insulin signaling may serve not only as a possible neuroprotective therapy in glaucoma, but also as a potential pro-regenerative one." (PMID 33925119, 2021). "A phase I trial using topical insulin for glaucoma patients is recruiting patients [NCT04118920]." (PMID 34589504, 2021). "This suggests that enhancing mitochondrial function may be an additional therapeutic benefit to targeting insulin signaling in glaucoma." (PMID 33925119, 2021). "Hence, insulin signaling in glaucoma has the potential to regenerate retracted RGC dendrites and enhance synaptic plasticity." (PMID 33925119, 2021). "Whether defective insulin signaling directly contributes to the pathogenesis of glaucoma or occurs secondarily as a consequence of neurodegenerative processes remains unclear." (PMID 33925119, 2021). "Insufficient insulin signaling may play a key role in the progression of glaucoma." (PMID 41584099, 2026). "This prospective study of once-daily topical insulin for glaucoma was conducted in 2 parts: an open-label dose escalation phase evaluating low (100 units/mL) and high doses (500 units/mL), followed by a randomized masked trial comparing low- and high-dose topical insulin." (PMID 41584099, 2026). "However, retinal ganglion cell dendrites are plastic, allowing for the reintegration of neuronal circuits (e.g. via BDNF or insulin treatment), and as such, dendritic recovery may provide a useful substrate for visual recovery in glaucoma." (PMID 39180087, 2024). "Additionally, retinal function may be increased through a pioglitazone-induced increase in insulin signaling, which may play a critical role in a number of glaucoma phenotypes, including mitochondrial dysfunction, astrocytic activity, and synaptic plasticity." (PMID 35204782, 2022).
glaucoma (continued). "Therefore, anti-inflammatory effects of insulin could potentially have a neuroprotective role in glaucoma." (PMID 33925119, 2021). "Hence, Aβ deposition is a pathological feature of glaucoma that may be a targeted therapeutically via restoration of insulin sensitivity and signaling." (PMID 33925119, 2021). "However, markers of glucose metabolism showed significant non-linear associations with glaucoma prevalence, including hockey-stick shaped associations for fasting insulin, HbA1c and HOMA-IR, and a J-shaped association for fasting glucose." (PMID 25393836, 2014). "In 2016, we delineated how sex steroids (e.g., estrogens, androgens), insulin, thyroid hormones, and melatonin modulate ocular tissue physiology, impacting conditions ranging from dry eye syndrome (DES) to glaucoma and age-related macular degeneration (AMD)." (PMID 40573278, 2025). "Recent data from topical application of insulin in a nonhuman primate glaucoma model protected against RNFL thinning in an eye more similar to human and thereby strongly support the plausibility of pharmacodynamic effect." (PMID 41584099, 2026). "Recent data supports the hypothesis that the topical administration of insulin can drive RGC dendritic recovery and enhance RGC function in a murine model of glaucoma." (PMID 39180087, 2024). "Although insulin has an important role to play in the treatment of corneal epitheliopathies, therapies (anti-glaucoma, antibiotic, anti-inflammatory) that do not adversely affect corneal re-epithelialization should not be overlooked." (PMID 38276493, 2023). "The downstream effectors of insulin signaling, particularly those of the PI3K/Akt pathway, are expressed in neuronal, glial, and vascular components of the retina and modulate various important functions that are disrupted in glaucoma." (PMID 33925119, 2021). "Insulin is neuroprotective in mouse and nonhuman primate models of glaucoma." (PMID 41584099, 2026). "Finally, when VFI was analyzed, values were not significantly modified in the metformin glaucoma group (p = 0.38), while there was a significant worsening in the insulin group (p = 0.03) comparing T0 to T6." (PMID 41285704, 2025). "Therefore, improving fatty liver and reducing insulin resistance could be a strategy to manage IOP and prevent glaucoma." (PMID 36364718, 2022). "However, the two forms of glaucoma respond differentially to carbohydrate ingestion, irrespective of insulin resistance." (PMID 29879162, 2018). "It will be important to look for evidence of insulin-mediated changes in inner plexiform layer/dendrites, or in metabolic function not seen in 1 month by FPF imaging, in human glaucoma patients in clinical trials incorporating longer treatment duration." (PMID 41584099, 2026).
lactic acidosis (37 papers, 2010 to 2026). Metabolic acidosis characterized by the accumulation of lactate in the body. "attempted to treat two patients with type B malignancy‐associated lactic acidosis with insulin and glucose in an attempt to increase the conversion of pyruvate to acetyl‐coenzyme A, and consequently facilitate the oxidation of lactate to pyruvate." (PMID 40152524, 2025). "Therapeutically, insulin, incretin analogs, and/or oral antidiabetic medications can be used, apart from metformin because of the increased risk of lactic acidosis." (PMID 39408828, 2024). "For instance, metformin has been associated with the risk of lactic acidosis in rare cases, and insulin therapy can lead to weight gain and other complications." (PMID 39184140, 2024). "Glycogenic hepatopathy can be associated with lactic acidosis, particularly following insulin treatment." (PMID 34419042, 2021). "Although buformin could significantly enhance cellular insulin sensitivity, it is prohibited in many markets because of the elevated risk of lactic acidosis." (PMID 33817229, 2020). "Accumulation of kidney-excreted drugs, especially sulfonylureas and insulin, may result in repeated hypoglycemic episodes, while metformin may cause potentially lethal lactic acidosis." (PMID 32235471, 2020). "With regard to acidosis complicating thyroid storm, while many reports have shown that thyroid storm can be complicated by ketoacidosis via the insulin antagonist actions of thyroid hormones, association of lactic acidosis with thyroid storm has rarely been reported." (PMID 20731531, 2010). "In our series the rapid resolution of lactic acidosis was predictable post administration of insulin analog." (PMID 38365663, 2024). "Administration of low-dose long-acting insulin glargine led to the resolution of the lactic acidosis, insulin resistance, and decreased requirements for pressor and inotropic support, which led to decreased need for mechanical circulatory support." (PMID 38365663, 2024). "The addition of low dose long acting-insulin analog led to the resolution of the lactic acidosis, significant decrease in the dose of infused regular insulin, as well as decrease of the required epinephrine dose." (PMID 38365663, 2024). "More recently, lactic acidosis was recognized as an additional feature, often induced by insulin treatment." (PMID 34419042, 2021). "Lactic acidosis has also been treated with intravenous administration of insulin, which increases the conversion of pyruvate to acetyl‐coenzyme A and consequently facilitates oxidation of lactate to pyruvate." (PMID 33611854, 2021). "During her admission, she was initially hyperglycaemic (blood sugars 22, reference range 3.9–5.9 mmol/L), had a persistent lactic acidosis, and required insulin and intravenous hydration." (PMID 34681037, 2021). "Serial measurements of arterial blood gases revealed persistent lactic acidosis and anion gap despite insulin and dextrose infusions." (PMID 27699071, 2016). "We believe that in hepatic phenotype of DLD deficiency the treatment cornerstone should be prevention/early treatment of metabolic decompensation by avoiding catabolism with sufficient early intravenous glucose intake, if necessary with insulin to avoid lactic acidosis." (PMID 39544687, 2024). "This study investigates the efficacy of using a long-acting insulin analog, along with the infusion of regular insulin, in achieving appropriate glycemic control and correcting lactic acidosis in patients post orthotopic heart transplant who demonstrate severe lactic acidosis and insulin resistance." (PMID 38365663, 2024). "Given that this dose of metformin can produce potentially toxic lactic acidosis in individuals with even moderate renal impairment, the immediate benefit and the scale of a significant reduction in insulin resistance after post-meal exercise is apparent and convincing." (PMID 34959894, 2021).
lactic acidosis (continued). "Combining metformin with insulin in non-cardiac surgical ICU patients is associated with better glucose control without the occurrence of lactic acidosis." (PMID 28558845, 2017). "This case demonstrates lactic acidosis exacerbated by high dose insulin and dextrose therapy." (PMID 27699071, 2016). "Given that large amounts of insulin and glucose are required for the development of glycogenic hepatopathy, this would explain the persistent and worsening lactic acidosis in our patient with typical DKA treatment of dextrose and insulin infusions." (PMID 27699071, 2016). "In our cohort, infusion of large doses of regular insulin did not lead to adequate glycemic control or correction of lactic acidosis." (PMID 38365663, 2024). "The direct action of CLZ on membrane proteins may play a role in lactic acidosis, specifically CLZ's suppression of calcium-dependent potassium permeability leading to decreased insulin secretion." (PMID 29670504, 2018). "Furthermore, the current study and meta-analyses show that the morbidity of lactic acidosis using metformin is not significantly different from other hypoglycemic treatments, such as sulfonylureas, insulin, and other oral hypoglycemic agents." (PMID 32316910, 2020).
leukemia (37 papers, 2005 to 2025). A malignant (clonal) hematologic disorder, involving hematopoietic stem cells and characterized by the presence of primitive or atypical myeloid or lymphoid cells in the bone marrow and the blood. "Dexamethasone is commonly used as the initial chemotherapy treatment for leukemia, but it has several side effects including insulin resistance and effects on fat storage, liver fat, and lipid fuel fluxes." (PMID 40285538, 2025). "In AML, leukemia cells have been shown to induce production of IGFBP1 from the adipose tissue to reduce insulin sensitivity and enhance their glucose uptake, favoring survival." (PMID 38159164, 2024). "IPT, which involves the use of insulin alongside low-dose chemotherapy, has gained global attention but requires additional investigation to determine its efficacy in treating leukemia." (PMID 38731097, 2024). "Further research is necessary to elucidate this connection and investigate the potential of insulin potentiation therapy (IPT) in leukemia treatment." (PMID 38731097, 2024). "Leukemia cells vary the body's systemic physiology by impairing both insulin secretion and insulin sensitivity in the host to provide increased glucose to leukemia cells." (PMID 32373530, 2020). "Previous studies show that activation of cofilin has a key role in mediating secretion in different tissues, including insulin secretion, parotoid exocrine secretion, platelet degranulation and histamine release from basophilic leukemia cells." (PMID 37138671, 2023). "The results of this study indicated that leukemia cells hijack host glucose by inducing IGFBP1 production from adipose tissue to mediate insulin sensitivity and by inducing gut dysbiosis, serotonin loss, and incretin inactivation to suppress insulin secretion." (PMID 37190210, 2023). "Some patients with leukaemia and nephrotic syndrome required daily insulin." (PMID 28125632, 2017). "Increased insulin concentration in the blood is the biochemical effect of elevated demand for glucose, which can be considered as one of the markers indicating the presence of cancer, especially leukemia." (PMID 25580464, 2014). "Several reports have demonstrated that CDK5 is also important for insulin secretion in pancreatic beta cells, differentiation of myogenic precursor cells, cell-matrix and cell-cell adhesion in lens epithelial cells, and survival of leukemia cells." (PMID 22768111, 2012). "Multiple levels of the signaling pathways of insulin and IGF-1 are of capital importance in the pathogenesis of leukemia." (PMID 38159164, 2024). "In other diseases such as leukemia, IGFBP1 is also abnormally elevated, which contributes to increased lipolysis in WAT and systemic insulin resistance." (PMID 35927268, 2022). "In support of this hypothesis, phosphorylated WNK1 was shown to block insulin-stimulated mitosis, and GDP366-induced phosphorylation of STMN1 promoted cell cycle arrest and apoptosis in leukemia cells." (PMID 37305581, 2023). "Disrupting this adaptive homeostasis attenuates leukemia progression, and that SCFAs inhibit leukemia-induced adaptive homeostasis by affecting the integrity of the intestinal epithelium and regulating IGFBP1 as well as insulin levels." (PMID 37190210, 2023). "In future research, it would be eligible to include studies of cell sensitization with insulin prior to Glu–MTX incubation to check whether insulin can promote GLUT transporters overexpression in lymphoma and leukemia cells to increase the cellular uptake of the conjugate." (PMID 33925555, 2021). "In addition, most patients in our study were not taking insulin at the time of leukemia diagnosis." (PMID 33437503, 2020).
malaria (37 papers, 2008 to 2025). Malaria is a serious and sometimes fatal disease caused by a parasite that commonly infects a certain type of mosquito which feeds on humans. "The INS/INS genotype of rs10562972 (FAS) was identified as a risk factor for malaria caused by P. vivax when compared to P. falciparum." (PMID 37794476, 2023). "Mosquito insulin signaling regulates nutrient metabolism and has been implicated in reduced prevalence and intensity of malaria parasite, Plasmodium falciparum, infection in mosquitoes." (PMID 29649225, 2018). "Located in the promoter region of the CASP8 gene, the INS/INS genotype significantly increases the susceptibility to malaria caused by P. falciparum, while the DEL/DEL genotype reduces the chances for mono-infection by P. falciparum and for infection by multiple species." (PMID 37794476, 2023). "In this context, it is important to recognise, as discussed, that the intravenous administration of quinine, as used in the treatment of malaria, stimulates insulin and can cause hypoglycaemia, indicating that a direct effect on the pancreas is likely to contribute to glucose lowering." (PMID 37630774, 2023). "Quinine administration in malaria patients, enhances the blood insulin levels resulting to decline in serum glucose concentration." (PMID 39492784, 2024). "Insulin treatment improves survival in mice infected with P. berghei, indicating its potential as an additional therapy for malaria." (PMID 39492784, 2024). "The intravenous administration of quinine (thus, bypassing the GI tract) for the treatment of malaria, in a dose of ~500 mg, has long been known to trigger hypoglycaemia in some patients, due to the potent stimulation of insulin." (PMID 37630774, 2023). "The KEGG analyses revealed that 16 malignant characteristics were enriched in the high-risk subgroup, such as hematopoietic cell lineage, cell adhesion molecules, insulin secretion, malaria, axon guidance, etc.." (PMID 35047414, 2021). "For example, laboratory studies have demonstrated that high levels of insulin supplementation increase parasite load and decrease the lifespan of the malaria vector Anopheles stephensi." (PMID 28700639, 2017). "Quinine treatments—one of the most efficacious anti-malaria treatments—are known to induce a release of insulin in the body, leading to hypoglycaemia." (PMID 28542578, 2017). "Above all, baseline HOMAB correlated positively with malaria-induced insulin level (R = 0.498; P = 0.025)." (PMID 25587486, 2014). "We have previously shown that ingested human insulin inhibits NF-κB-dependent immunity in A. stephensi leading to increased malaria parasite development." (PMID 24968248, 2014). "The regression models highlight the most significant factors that determine birth weight, including maternal total cholesterol, malaria status and cord insulin and IGF-I levels." (PMID 22429464, 2012). "In the setting of endemic malaria, maternal total cholesterol during pregnancy and cord blood insulin and IGF-I levels are potential biomarkers of foetal growth and birth size." (PMID 22429464, 2012). "In the setting of endemic malaria, maternal total cholesterol during pregnancy and cord blood insulin and IGF-I levels are important markers of foetal growth restriction and reduced birth size likely mediated through placental insufficiency." (PMID 22429464, 2012). "The use of glucose tolerance test may have provided a better view of the body’s response to postprandial insulin in malaria." (PMID 40802820, 2025). "Placental malaria can impair insulin production, resulting in elevated blood glucose levels." (PMID 39492784, 2024). "For other infectious diseases, such as malaria, the presence of human hormones, cytokines, and growth factors (such as glucose and insulin) in the infectious blood meal can indeed alter the course of infection, hereby affecting vector physiology and parasite transmission." (PMID 35385472, 2022).